DPYD (dihydropyrimidine dehydrogenase)
Diseases named in the same sentence as DPYD in open-access papers (continued):
Sharing a sentence is not in itself a finding about the gene and the disease.
tumor (82 papers, 2002 to 2026). "Gimeracil functions by inhibiting dihydropyrimidine dehydrogenase activity, causing heightened fluorouracil levels in both the bloodstream and tumor tissue." (PMID 39409992, 2024). "On the other hand, the expression levels of CIAO1 and DPYD in CM have demonstrated a positive correlation with tumor prognostic risk." (PMID 38874871, 2024). "The incomplete expression of dihydropyrimidine dehydrogenase and total deficiency of Bcl-2 are considered to be the main underlying causes of such extraordinary chemosensitivity and so severe a tumour lysis phenomenon." (PMID 32582369, 2020). "As for DPYD, we and other groups identified it as a promoter of tumor development, and high DPYD expression was closely associated with poor patient prognosis." (PMID 29358721, 2018). "Over-expression of thymidylate synthase (TS) and dihydropyrimidine dehydrogenase (DPD) in tumor tissue is associated with insensitivity to 5-fluorouracil (5-FU)." (PMID 19105824, 2008). "In addition to screening for well-known DPYD variants, there is growing interest in incorporating DPYD testing into routine tumour sequencing, particularly for patients receiving fluoropyrimidine-based chemotherapy." (PMID 41562939, 2026). "Tumor expression of DPYD has been linked to resistance to fluoropyrimidines." (PMID 38028629, 2023). "Interestingly, elevated DPYD expression was identified to be closely associated with larger tumor size (P = 0.004), tumor recurrence (P < 0.001), and advanced tumor node metastasis (TNM) stage (P = 0.041)." (PMID 29358721, 2018). "Elevated DPYD expression was validated in PAAD tissues and cell lines, and functional assays demonstrated that DPYD knockdown inhibited tumor cell clonogenicity, migration, and disrupted key metabolic pathways." (PMID 41832427, 2026). "The tumor-inhibiting factor miR-494 is capable of directly binding to DPYD and exerting a negative regulatory effect on its expression, thereby enhancing the apoptosis of CRC cells induced by 5-FU." (PMID 39935428, 2025). "The rate-limiting step in the catabolism of 5-FU in both normal and tumour cells is the conversion of 5-FU to dihydrofluorouracil, which is mediated by dihydropyrimidine dehydrogenase (DPD)." (PMID 39618581, 2024). "Although there is increasing evidence to a link between DPYD and tumor, little is known about the role of DPYD in HCC progression." (PMID 29358721, 2018). "Our data showed that DPYD is a potential tumor promoter that is distinctly upregulated, and potently promotes aggressiveness of HCC by regulating EMT process." (PMID 29358721, 2018). "In this retrospective study, sex, age, primary tumor location, chemotherapy regimens, line of treatment, and UGT1A and DPYD polymorphisms were included in the analysis." (PMID 28637434, 2017). "Geimidine has a strong and effective dihydropyrimidine dehydrogenase (DPD) selective antagonistic effect, thus inhibit 5-FU catabolism, maintain high concentration of fluorouracil in tumor tissue and enhance antitumor effect of fluorouracil." (PMID 29113401, 2017). "Gimeracil reversibly inhibits dihydropyrimidine dehydrogenase (DPD), a catabolic enzyme of 5-fluorouracil, and thereby increases concentrations of 5-fluorouracil in serum and tumor tissue." (PMID 26353772, 2015). "Significant genetic losses were assumed to contain potential tumour-suppressor genes: DPYD (1p21.3); CLDN22, CLDN24, ING2, CASP3, SORBS2 (4q34.2-q35.1); DEFB (8p23.1)." (PMID 26019623, 2015). "A large number of important genetic determinants have been identified thus far in tumours but only a few of them (TS and dihydropyrimidine dehydrogenase) have been tested prospectively." (PMID 17339891, 2007).
tumor (continued). "Interference with DPD activity through methylation of the promoter of the DPYD gene, which encodes the DPD protein, or DPD inhibitors such as 5-ethynyluracil and 5-chloro-2,4-dihydroxypyridine (CDHP) can improve the anti-tumor activity of 5-FU to a greater extent." (PMID 41276852, 2025). "Gimeracil inhibits dihydropyrimidine dehydrogenase, resulting in increased fluorouracil levels in the bloodstream and tumor tissues, whereas potassium terbacil reduces gastrointestinal toxicity by preventing fluorouracil phosphorylation in the gastrointestinal tract." (PMID 40361375, 2025). "In contrast, DPYD expression was associated with neither tumor response nor overall survival in patients treated with MVAC." (PMID 35595780, 2022). "Dihydropyrimidine dehydrogenase (DPD) tumour expression may provide added value to human equilibrative nucleoside transporter-1 (hENT1) tumour expression in predicting survival following pyrimidine-based adjuvant chemotherapy." (PMID 29515256, 2018). "Differences in catabolism of 5-FU in tumour via dihydropyrimidine dehydrogenase (DPD) can also be ruled out since DPD was not detectable in either tumour variant." (PMID 12915890, 2003). "When evaluated in patients treated with 5-fluorouracil or 5-fluorouracil derivatives, patients with dihydropyrimidine dehydrogenase-positive tumours had a significantly (P<0.05) poorer disease-free survival compared to those with dihydropyrimidine dehydrogenase-negative tumour." (PMID 11870510, 2002). "Therefore, the expression and function of DPYD, TYMS, MTHFR, ERCC1, ERCC2, XRCC1, and GSTP1 may be influenced not only by genetic polymorphisms, but also by processes that are specific for the tumor tissue." (PMID 33429840, 2021). "CDHP acts as a competitive inhibitor of the enzyme dihydropyrimidine dehydrogenase (DPD), thereby limiting the degradation of 5-FU and resulting in prolonged, efficacious concentrations of 5-FU in both plasma and tumor tissue." (PMID 40047784, 2025). "Initial molecular characterization of the primary tumor demonstrated wild-type status for both RAS and BRAF, preserved dihydropyrimidine dehydrogenase (DPD) activity, and a microsatellite stable (MSS) phenotype." (PMID 40842629, 2025). "Possible mechanisms included suppression of NF-kB nuclear translocation and I-kB phosphorylation and dihydropyrimidine dehydrogenase (DPD) downregulation to slow down drug metabolism, which boosted the anti-tumor efficacy of low dose 5-Fu in MGC803 cells." (PMID 40052129, 2025). "On the one hand, previous studies found a strong correlation between DPYD mRNA expression with DPD activity in liver sections and in tumor tissue." (PMID 34442436, 2021). "S-1 contains CDHP (5-chloro-2,4-dihydroxypyridine), which is a more potent inhibitor of dihydropyrimidine dehydrogenase (DPYD) than uracil in UFT, resulting in the maintenance of a high concentration of 5-FU in the tumor tissues." (PMID 28417167, 2017). "Dihydropyrimidine dehydrogenase (DPD)-mediated conversion of 5-FU to dihydrofluorouracil (DHFU) is the rate-limiting step of 5-FU catabolism in normal and tumor cells." (PMID 18794772, 2008). "CDHP inhibits the activity of dihydropyrimidine dehydrogenase (DPD), an enzyme that degrades 5-FU, with about 180-fold more potency than uracil, thereby maintaining prolonged blood and tumour 5-FU concentrations." (PMID 18362933, 2008). "The enzyme dihydropyrimidine dehydrogenase (DPD) regulates the FU catabolic route in liver and, importantly, at the tumoural cell level." (PMID 11953866, 2002).
tumor (continued). "This phenomenon may constitute an underexplored mechanism of chemoresistance in tumor cells under EMT, implying that expression of the genes DPYD, TYMS, MTHFR, ERCC1, ERCC2, XRCC1, and GSTP1 may be modulated EMT-TFs." (PMID 33429840, 2021). "Afterwards, immunohistochemical study of the tumour specimen confirmed moderate positivity of dihydropyrimidine dehydrogenase and absence of Bcl-2 expression." (PMID 32582369, 2020).
adenocarcinoma (3 papers, 2015 to 2025). A common cancer characterized by the presence of malignant glandular cells. "S-1 increases the blood 5-FU concentration by inhibiting the metabolism of 5-FU by means of dihydropyrimidine dehydrogenase (DPD) and shows significant effectiveness to adenocarcinoma with high-DPD activity of the stomach, pancreas, biliary tract, and so on." (PMID 26943382, 2015).
cardiovascular disease (1 paper, 2023). "The combination might be an alternative especially for patients with significant cardiovascular disease or a complete lack of dihydropyrimidine dehydrogenase, avoiding capecitabine (CAPTEM) and 5-FU (FOLFOX)." (PMID 37872405, 2023).
Gastrointestinal Tumors (1 paper, 2024). "In the present study, we examined the association of five common variants in the DPYD gene with severe FP-related toxicity in patients with gastrointestinal tumors." (PMID 39126072, 2024).
infection (1 paper, 2020). The state of being infected such as from the introduction of a foreign agent such as serum, vaccine, antigenic substance or organism. "Functional studies will be required to assess the role of DPYD in host defense against infection and to determine the effects of the SNPs on the regulation of gene expression and on DPYD activity." (PMID 32127447, 2020).
Mendelian diseases (1 paper, 2014). "In addition to FANCM, we further evaluated evidence for two other genes COL9A2 and DPYD that were previously implicated in other Mendelian diseases." (PMID 25078778, 2014).
DPYD also shares sentences with these, for which no sentence is quoted: hepatocellular carcinoma (5 papers); head and neck squamous cell carcinoma (3); lung adenocarcinoma (3); metastatic colorectal cancer (3); stomatitis (3); autism spectrum disorder (2); biliary tract cancer (2); Gastric tumors (2); kidney disease (2); metastasis (2); non-small cell lung carcinoma (2); Obesity (2); pancreatic ductal adenocarcinoma (2); anal carcinoma (1); anaplastic glioma (1); Autosomal Dominant Mental Retardation 21 (1); bipolar disorder (1); ciliopathies (1); diabetic nephropathy (1); endometrial cancer (1); fibrosarcoma (1); Gait ataxia (1); gastric adenocarcinoma (1); heart failure (1); infectious disease (1); ischemic stroke (1); Krabbe disease (1); lactic acidosis (1); Leukoencephalopathy (1); melanoma (1).
A further 17 diseases each share a sentence with DPYD in 1 paper.